RBMS3 (RNA binding motif single stranded interacting protein 3)
Diseases named in the same sentence as RBMS3 in open-access papers (continued):
Sharing a sentence is not in itself a finding about the gene and the disease.
cancer (21 papers, 2013 to 2025). A tumor composed of atypical neoplastic, often pleomorphic cells that invade other tissues. "Tumorigenesis is an age-associated process, and reduced RBMS3 expression has been linked to poor prognosis in various cancers." (PMID 40417629, 2025). "RBMS3 has been found to play a crucial role in development, including embryonic pancreas, neural tube, and dorsal root ganglion 16, and its abnormal expression has been associated with the initiation and progression of various cancers 18-21." (PMID 37781074, 2023). "Moreover, low expression of RBMS3 has been associated with poor prognosis in cancer patients." (PMID 38618967, 2024). "However, the exact mechanism underlying RBMS3 regulation in cancer remains to be fully elucidated." (PMID 37781074, 2023). "An increased expression of RBMS3 was corelated with HER2(+) cancer specimens (p < 0.05) and ER(−) cancer specimens (p < 0.05)." (PMID 36769184, 2023). "The statistical analysis revealed a significantly decreased RBMS3 expression in the cancer specimens when compared with the mastopathy tissues (p < 0.001)." (PMID 36769184, 2023). "RBMS3, an RNA-binding protein, participates in various processes, such as embryogenesis, cancer initiation and progression." (PMID 37968257, 2023). "Expression of RBMS3 in the stroma of the cancer cases was significantly higher than in the control specimens (Mann–Whitney test p < 0.0001)." (PMID 36769184, 2023). "RBMS3 expression in the stroma of IDC was significantly higher than in the cancer cells (Mann–Whitney test p < 0.0001)." (PMID 36769184, 2023). "To elucidate the fundamental landscape of RBMS3 expression in cancer, we conducted a transcriptional analysis of RBMS3 in the TCGA and GTEx databases." (PMID 37781074, 2023). "In recent studies, authors have provided data that point to the fact that a certain level of RBMS3 is necessary for cancer progression." (PMID 36769184, 2023). "Our results suggest that further studies should be conducted to consider the differences in RBMS3 expression correlated with receptor expression in cancer cells and stromal cells." (PMID 36769184, 2023). "RNA-binding protein 3 (RBMS3) plays a significant role in embryonic development and the pathogenesis of many diseases, especially cancer initiation and progression." (PMID 36142783, 2022). "In several of the previously discussed types of cancer, the Wnt/β-catenin pathway was inhibited by RBMS3’s expression." (PMID 36142783, 2022). "RBMS3’s ability to suppress the growth and progression of different types of cancers makes it an interesting potential target for the development of novel anticancer therapies." (PMID 36142783, 2022). "From 2008 onwards, RBMS3 has become a potential prognostic marker of different types of cancer and a factor regulating the process of carcinogenesis." (PMID 36142783, 2022). "The molecular mechanisms underlying these effects include the impact on the Wnt/β-catenin pathway and the cell cycle, confirmed by the inhibited expression of β-catenin, c-Myc, and cyclin D1 in RBMS3 expressing cancer cells." (PMID 36142783, 2022). "From that time onwards, RBMS3 has significantly grown in popularity and importance as a potential marker and regulator in many different types of cancer." (PMID 36142783, 2022). "Its’ predicted parental gene target using circBase is RBMS3, which has previously been identified to suppress cell proliferation, migration, invasion, and angiogenesis in a number of different cancers." (PMID 33718350, 2021). "Knockdown of RBMS3 increased cancer cells migration ability, while overexpression of RBMS3 repressed cancer cell migration and invasion in vitro and inhibited lung metastases in vivo." (PMID 30819235, 2019). "From our study, we call for further researches of the molecular mechanisms of HIF1A location, which will likely provide new insights into the pivotal function of RBMS3 in cancer biology and should provide a novel approach to the treatment of GC." (PMID 27902480, 2017).
cancer (continued). "One target, RNA-binding motif, single-stranded-interacting protein 3 (RBMS3), is known to bind the c-Myc promotor and reduce cell proliferation through alteration of β-catenin expression in at least two types of human cancer." (PMID 28439397, 2017). "Furthermore, AMPK activation induced by metformin promotes RBMS3 expression and inhibits cancer cell invasion and migration in an RBMS3-dependent manner." (PMID 37781074, 2023). "Furthermore, the statistical analysis of the clinical data together with the immunohistochemical expression of RBMS3 showed a significantly increased expression of RBMS3 in the cancer cells of the HER2 positive cases (Mann–Whitney test p < 0.05)." (PMID 36769184, 2023). "In addition, a statistically significant higher expression of RBMS3 was observed in cancer stromal cells in comparison to the control and cancer cells (p < 0.0001)." (PMID 36769184, 2023). "EMT plays a vital role in cancer progression, in which RBMS3 is a new potential regulator." (PMID 36142783, 2022). "Artificially increased expression of RBMS3 utilizing genome editing techniques may potentially improve the outcome of standard therapies in many types of cancers." (PMID 36142783, 2022). "These molecular characteristics make RBMS3 a promising biomarker of OS and a prognostic factor in neoplastic processes, where statistical data support this statement for many different types of cancer." (PMID 36142783, 2022). "It is also significant that RBMS3 may act as a prognostic factor of overall survival (OS) in different types of cancer." (PMID 36142783, 2022). "The RNA‐binding motif single‐stranded interacting protein 3 (RBMS3) gene, a constituent of the RBM protein family, is situated within the p23‐p24 region of human chromosome 3, with frequent observations of deletion or mutation in cancer, underscoring its pivotal contribution to cancer advancement." (PMID 38618967, 2024). "RBMS3′s anticancer function could be related to the mechanisms that regulate adhesiveness and invasiveness, which are also associated with the EMT process in cancer." (PMID 36769184, 2023). "The analysis of the immunohistochemical expression of RBMS3 in 490 cases of IDC and 26 cases of mastopathy showed a statistically significant decrease in RBMS3 expression in the cancer specimens compared to the mastopathy samples (Mann–Whitney test p < 0.001)." (PMID 36769184, 2023). "Research findings have illustrated the involvement of RBMS3 in the process of epithelial-mesenchymal transition (EMT), thereby suppressing distant metastasis of cancers." (PMID 37781074, 2023). "Another potential use of RBMS3 is as a target for anticancer drugs, thanks to its function as TSG and its proven ability to suppress cancer migration and invasive abilities." (PMID 36142783, 2022). "Other RBM proteins family members also participate in suppressing proliferation in different cancers, such as RBM6, RBMS1, RBMS2, RBMS3, etc.." (PMID 34804951, 2021). "Another downstream target regulated by RBMS3 in GC is the basic helix-loop-helix-PAS transcription factor α (HIF1-A) subunit of the HIF-1 protein, responsible for the induction of VEGF expression in cancer cells." (PMID 36142783, 2022). "Down-regulation of RBMS3 and up-regulation of HIF1A have been reported in some human cancers." (PMID 27902480, 2017). "Interestingly, other cell-cycle-related proteins, such as CDK2 or cyclin E or D1, dysregulated in other types of cancer, do not seem to be involved in RBMS3’s role in ESCC." (PMID 36142783, 2022).
infection (1 paper, 2017). The state of being infected such as from the introduction of a foreign agent such as serum, vaccine, antigenic substance or organism. "Three lentiviral shRNA constructs (shRBMS3-1, shRBMS3-2 and shRBMS3-3) designed against different regions of RBMS3 were introduced separately into AGS, BGC-823 and MKN-45 cells via infection." (PMID 27902480, 2017). "RBMS3 stably overexpressed or silenced AGS, BGC-823 and MKN-45 cells were established by lentiviruses infection, while the empty vector (NC) or shRNA targeting LacZ (shLacZ) served as control groups respectively." (PMID 27902480, 2017).
neurological disease (1 paper, 2018). "RBMS3 had significantly increased protein expression levels in ALS cerebellum and spinal cords compared to non-neurological disease controls, recapitulating observed increased cerebellar interneuronal staining." (PMID 29134320, 2018).
renal disease (1 paper, 2022). "RBMS3 is most highly expressed in the arteries and muscles, with low expression in the kidney cortex, and is not known from the literature to be involved in platinum pathways or renal disease." (PMID 35743677, 2022).
RBMS3 also shares sentences with these, for which no sentence is quoted: lung squamous cell carcinoma (5 papers); glioblastoma (2); prostate carcinoma (2); age-related macular degeneration (1); Autoimmunity (1); breast tumors (1); ependymoma (1); gall bladder carcinoma (1); intervertebral disk degenerative disorder (1); leukemia (1); microcephaly (1); myopia (1); primary angle-closure glaucoma (1); Sjögren’s syndrome (1); Strabismus (1); teratospermia (1).